PDCD6IP (programmed cell death 6 interacting protein)
Description:
Multifunctional protein involved in endocytosis, multivesicular body biogenesis, membrane repair, cytokinesis, apoptosis and maintenance of tight junction integrity. Class E VPS protein involved in concentration and sorting of cargo proteins of the multivesicular body (MVB) for incorporation into intralumenal vesicles (ILVs) that are generated by invagination and scission from the limiting membrane of the endosome. Binds to the phospholipid lysobisphosphatidic acid (LBPA) which is abundant in MVBs internal membranes. The MVB pathway requires the sequential function of ESCRT-O, -I,-II and -III complexes. The ESCRT machinery also functions in topologically equivalent membrane fission events, such as the terminal stages of cytokinesis. Adapter for a subset of ESCRT-III proteins, such as CHMP4, to function at distinct membranes. Required for completion of cytokinesis. May play a role in the regulation of both apoptosis and cell proliferation. Regulates exosome biogenesis in concert with SDC1/4 and SDCBP. By interacting with F-actin, PARD3 and TJP1 secures the proper assembly and positioning of actomyosin-tight junction complex at the apical sides of adjacent epithelial cells that defines a spatial membrane domain essential for the maintenance of epithelial cell polarity and barrier (By similarity). (Microbial infection) Involved in HIV-1 virus budding. Can replace TSG101 it its role of supporting HIV-1 release; this function requires the interaction with CHMP4B. The ESCRT machinery also functions in topologically equivalent membrane fission events, such as enveloped virus budding (HIV-1 and other lentiviruses).
Synonyms: AIP1; ALIX; Hp95; DRIP4; MCPH29
Tractability: Small molecule: it has a binding pocket of medium quality. Antibody: UniProt places it where antibodies can reach, with high confidence; its Gene Ontology location is reachable by antibodies, with medium confidence. PROTAC: ubiquitination databases record sites on it; its protein half-life has been measured.
Gene: Protein-coding gene on chromosome 3 (33,798,571 to 33,869,707, forward strand). Ensembl gene ENSG00000170248.
Subcellular location: Cytoplasm, cytosol; Melanosome; Cytoplasm, cytoskeleton, microtubule organizing center, centrosome; Secreted, extracellular exosome; Cell junction, tight junction; Midbody, Midbody ring
Subcellular location (Human Protein Atlas): Vesicles; Centrosome
Pathways (Reactome):
Disease: Budding and maturation of HIV virion; Dengue Virus-Host Interactions; Uptake and function of anthrax toxins
Programmed Cell Death: RIPK1-mediated regulated necrosis; Regulation of necroptotic cell death
Gene Ontology:
Molecular function: calcium-dependent protein binding; protein binding; protein homodimerization activity; proteinase activated receptor binding
Biological process: endosome transport via multivesicular body sorting pathway; midbody abscission; mitotic cytokinesis; mitotic metaphase chromosome alignment; nucleus organization; positive regulation of exosomal secretion; positive regulation of extracellular exosome assembly; protein homooligomerization; regulation of centrosome duplication; regulation of extracellular exosome assembly; regulation of mitotic spindle assembly; viral budding; viral budding via host ESCRT complex; actomyosin contractile ring assembly; bicellular tight junction assembly; extracellular exosome biogenesis; macroautophagy; maintenance of epithelial cell apical/basal polarity; multivesicular body assembly; regulation of membrane permeability
Cellular component: centrosome; endoplasmic reticulum exit site; extracellular exosome; extracellular vesicle; Flemming body; focal adhesion; immunological synapse; melanosome; membrane; actomyosin; cytosol; bicellular tight junction; cytoplasm; extracellular region
Genetic constraint (gnomAD): Loss-of-function variants: 25 observed, 59.91 expected, observed/expected ratio (o/e) 0.42, 90% interval 0.3 to 0.58. The upper end of that interval is the gene's LOEUF score, 0.58, which puts it in group 2 of 6, group 1 being the genes least tolerant of losing a copy. Missense variants: 658 observed, 740.72 expected, observed/expected ratio (o/e) 0.89, 90% interval 0.83 to 0.95. Synonymous variants: 264 observed, 275.33 expected, observed/expected ratio (o/e) 0.96, 90% interval 0.87 to 1.06.
Homologues: Orthologues: chimpanzee PDCD6IP (99% identical), macaque PDCD6IP (99% identical), dog PDCD6IP (96% identical), tropical clawed frog pdcd6ip (74% identical).
Diseases named in the same sentence as PDCD6IP in open-access papers:
PDCD6IP is named in the same sentence as 56 diseases in open-access papers, as found by Europe PMC text mining. Sharing a sentence is not in itself a finding about the gene and the disease. The quoted sentences say what the papers report.
melanoma (6 papers, 2016 to 2024). A malignant, usually aggressive tumor composed of atypical, neoplastic melanocytes. "PDCD6IP (ALIX), which was highly expressed in melanoma-specific sEVs of progressing patients, had the strongest discriminating power." (PMID 35804857, 2022). "Remarkably, despite the small patient numbers in each cohort, PDCD6IP (ALIX) emerged as the protein with the greatest power for discriminating melanoma patients with PD from patients with NED/SD." (PMID 33613873, 2021). "Investigating negative-regulated target genes, we found eight genes (ANKRD13C, ARL5A, ATL3, PAWR, PDCD6IP, SLC16A7, TFAM, UBP1) presenting a significant inverse correlation with miR-181a/b expression also in melanoma A375 sensitive cells." (PMID 33670365, 2021). "Among the 12 MTEX‐upregulated proteins with higher expression in PD patients, PDCD6IP (ALIX, ALG 2‐interacting protein X) discriminated best (P = 0.0003) between the two groups of melanoma patients." (PMID 33613873, 2021). "Hence, the molecular signature of MTEX consisting of PDCD6IP/ALIX, 4 correlated proteins (HSP90AB1, TUBB, TUBB1, and PFN1) highly expressed in MTEX of patients with PD, plus CNTN1 and TGF‐β1 with differential distribution in MTEX of PD vs NED/SD patients may have prognostic significance in melanoma." (PMID 33613873, 2021).
pancreatic cancer (6 papers, 2021 to 2024). "In line with our findings, tissue expression of PDCD6IP in liver metastasis of pancreatic cancer has been found to also correlate with improved prognosis in patients with PDAC in the study of Law et.al35." (PMID 36993200, 2024). "We further noticed that some proteins such as PDCD6IP, SERPINA12, KRT20 showed statistically significant population-wise enrichment in pancreatic cancer compared to benign pancreatic diseases." (PMID 36993200, 2024).
prostate carcinoma (6 papers, 2013 to 2022). A carcinoma that arises from epithelial cells of the prostate gland. "In this study, we investigated differences in expression of XPO1 and PDCD6IP on well‐characterized prostate cancer cohorts using mass spectrometry and tissue microarray (TMA) immunohistochemistry to determine their diagnostic and prognostic value." (PMID 31018022, 2019). "There was a trend for lower expression of ALIX (PDCD6IP) to stratify patients with increased prostate cancer recurrence (P = 0.059), and reduced expression of Syntaxin 12 (STX12) was also indicative of at-risk patients, with significant stratification (P = 0.001)." (PMID 26473288, 2015). "Of note is the presence of several well-known exosomal proteins within the top echelon (i.e. CD9, TSG101, Alix/PDCD6IP) and interestingly, CD9 was increased in prostate cancer samples." (PMID 26196085, 2015). "Identification of exosomal proteins using high performance LC-FTMS resulted in the discovery of PDCD6IP, FASN, XPO1 and ENO1 as new candidate biomarkers for prostate cancer." (PMID 24391718, 2013). "There was a significant reduction of PDCD6IP mRNA in indolent cancer tissue when compared to both non-malignant and aggressive prostate cancer tissue (P ≤ 0.05 respectively)." (PMID 26473288, 2015). "In the current study, quantitation of gene signatures for the early endosomal genes APPL1, EEA1 and RAB5A, and analysis of the endosomal genes MYO1B, PDCD6IP and STX12 in prostate cancer patients expressing PSA ≤ 10 ng/mL, led to patient stratification into high and low-risk recurrence groups." (PMID 26473288, 2015).
microcephaly (4 papers, 2018 to 2025). A congenital or acquired developmental disorder in which the circumference of the head is smaller than normal for the person's age and sex. "Here, we report an unrelated individual with mild intellectual disability and microcephaly carrying a homozygous nonsense variant in PDCD6IP." (PMID 40897677, 2025). "Our case highlights the importance of including PDCD6IP as a disease‐causing gene in patients with intellectual disability and microcephaly." (PMID 40897677, 2025). "This additional case of biallelic PDCD6IP variants further supports its role in a novel neurodevelopmental disorder with microcephaly." (PMID 40897677, 2025). "Among the genes related to cerebellar volume in the four substructure GWASs we find genes related to ataxia (PEX7, MRPS27, PTK2), neurodevelopment (YPEL3, CASP6, TRIM11, GNB5) and microcephaly (PDCD6IP, USP28)." (PMID 35546225, 2022). "Although additional unrelated cases are lacking, microcephaly observed in Pdcd6ip knockout mice and pdcd6ip knockdown zebrafish supports the pathogenicity of PDCD6IP loss‐of‐function variants." (PMID 40897677, 2025). "Unlike previously reported familial cases with PDCD6IP biallelic variants, the individual described herein had acquired microcephaly, mild CPK elevation, and no epilepsy." (PMID 40897677, 2025). "There were also consistent morphological defects such as microcephaly and cardiac oedema that were specific and concentration dependent to the PDCD6IP AUGMO and to a lesser extent the PDCD6IP SBMO compared to the control." (PMID 30564460, 2018).
Arthritis (2 papers, 2019 to 2025). Inflammation of a joint. "However, the SDN map identified five cSABPs (ENO1, FTL, IMMT, PDCD6IP and HSPA6) that were associated with various types of arthritis." (PMID 31511554, 2019).
anaplastic astrocytoma (1 paper, 2017). "Significant increases in IGF2R were observed in diffuse and anaplastic astrocytomas and oligodendrogliomas, increased PDCD6IP in diffuse and anaplastic astrocytomas, and increased ANXA1 in anaplastic astrocytomas relative to normal brain." (PMID 27770278, 2017).
diabetes mellitus (1 paper, 2023). A metabolic disorder characterized by abnormally high blood sugar levels due to diminished production of insulin or insulin resistance/desensitization. "Ten potential target genes were identified, out of which three common potential target genes (CCDC28b, PDCD6IP, and USP34) were selected, which are most effective for cardiovascular diseases, diabetes mellitus, IBD, and PCOS." (PMID 38283897, 2023).
Intellectual disability (1 paper, 2025). "A homozygous truncating variant in PDCD6IP was recently reported in two siblings with primary microcephaly, intellectual disability, and short stature from a consanguineous Saudi family." (PMID 40897677, 2025).
osteoarthritis (1 paper, 2023). A noninflammatory degenerative joint disease occurring chiefly in older persons, characterized by degeneration of the articular cartilage, hypertrophy of bone at the margins and changes in the synovial membrane. "Four target genes (LMNA, MSN, PDCD6IP, and GAPDH) with five miRNAs (hsa-let-7a-5p, hsa-let-7b-5p, hsa-mir-15a-5p, hsa-mir-26a-5p, and hsa-mir-23b-3p) were associated with the pathway in osteoarthritis according to the results of the miRNet network analysis." (PMID 38132172, 2023).
pancreatic diseases (1 paper, 2021). "Four proteins were significantly higher in PC compared with other pancreatic diseases, including PDCD6IP (also known as ALIX), GPRC5B, SDCBP, and IST1." (PMID 34026608, 2021).
tumor (32 papers, 2011 to 2026). "Other established small EV markers such as the programmed cell death 6 interacting protein (PDCD6IP or ALIX) and the tumor susceptibility marker TSG101 known for its role in vacuolar sorting and small EV biogenesis were also detected." (PMID 40440285, 2025). "Among these, 14-3-3ε—implicated in tumor invasiveness and metastasis—and PDCD6IP/ALIX—a key regulator of EGFR activity and immune checkpoint trafficking—were also validated by Western blot analysis." (PMID 41441336, 2025). "Gene levels corresponding to invasion-related EV proteins showed that five genes (annexin A1, actin-related protein 3, integrin-β1, insulin-like growth factor 2 receptor and programmed cell death 6-interacting protein) were significantly higher in GBM tumours." (PMID 36071478, 2022). "Also, we verified that all the patients’ ascites EVs displayed EV-positive markers of CD63 and PDCD6IP (ALIX) proteins and tumour metastasis markers of N-cadherin (CDH2), claudin-1 (CLDN1) and angiogenin (ANG)." (PMID 40993350, 2025). "PDCD6IP has scarcely been reported as a tumor marker or as having a role in tumor biology." (PMID 31018022, 2019). "This is supported by observations that tumours cells produce more exosomes per cell than normal cells and PDCD6IP and ACTR3 levels are higher in GBM tumours compared to normal tissue." (PMID 27770278, 2017).
cancer (29 papers, 2009 to 2025). A tumor composed of atypical neoplastic, often pleomorphic cells that invade other tissues. "Currently, little information is available regarding the association between PDCD6IP polymorphisms and cancer risk." (PMID 26063962, 2015). "To date, there have only been two reports that investigated the association between PDCD6IP 15 bp I/D and cancer risk." (PMID 26063962, 2015). "PDCD6IP was significantly decreased in metastatic prostate tissue when compared with both primary cancer and PIN tissue (P ≤ 0.01)." (PMID 26473288, 2015). "Finally, only one protein-coding genes, PDCD6IP, colocalized strongly with the cancers (PP.H4 > 0.80) and was identified as HCG." (PMID 38659038, 2024). "The C-terminal tail of CHMP4C was recently shown to be bound by the apoptosis inhibitor PDCD6IP, suggesting that the cancer-specific splice form of CHMP4C may have altered binding behavior with PDC6IP." (PMID 19180177, 2009). "Based on this controversy, we can conclude that the PDCD6IP gene product might have different effects on the regulation of apoptosis in different populations or that apoptosis might have different regulatory effects on cancer progress in different types of cancer." (PMID 26063962, 2015). "For non-cancer studies, the miDRB-targeted exosome biogenesis genes for ferroptosis-inhibiting miRNAs are retrieved as follows: miR-19a-3p (SDC1, VPS4B, and MYO5B), miR-424-5p (VPS4A and MYO5B), miR-4291 (ATP9A, SMPD3, TSG101, and MYO5B), miR-522-3p (PDCD6IP), and miR-670-3p (CD34 and RAB27A)." (PMID 38892270, 2024).
neurodevelopmental disorder (2 papers, 2018 to 2025). A behavioral and cognitive disorder with onset during the developmental period that involves impaired or aberrant development of intellectual, motor, or social functions. "The PDCD6IP gene has not been previously implicated in any neurodevelopmental disorder and presented a unique opportunity from this study to assess the likely pathogenicity of this deletion in an animal model." (PMID 30564460, 2018).
PDCD6IP also shares sentences with these, for which no sentence is quoted: breast carcinoma (16 papers); infection (16); viral infection (6); non-small cell lung carcinoma (3); colorectal cancer (2); cyst (2); Flavivirus Infections (2); glioma (2); hepatocellular carcinoma (2); Hydrocephalus (2); lung carcinoma (2); nasopharyngeal carcinoma (2); adenocarcinoma (1); adenoma (1); Alzheimer disease (1); anemia (1); Ataxia (1); autism (1); autoimmune disease (1); breast adenocarcinoma (1); CADASIL (1); cardiovascular diseases (1); colon cancer (1); COVID-19 (1); Epstein-Barr virus infection (1); esophageal squamous cell carcinoma (1); gastric cancer (1); head and neck cancer (1); kidney injury (1); mood disorder (1).
A further 13 diseases each share a sentence with PDCD6IP in 1 paper.